GPC3 (glypican 3)
Diseases named in the same sentence as GPC3 in open-access papers (continued):
Sharing a sentence is not in itself a finding about the gene and the disease.
cancer (continued). "We hope this review will provide a theoretical basis for new therapeutic strategies targeting GPC3 to treat diseases including cancer." (PMID 40422229, 2025). "To overcome the heterogeneity of individual cancers and apply the antibody to a wide range of solid cancer patients, we collected five common cancer membrane protein antigens, such as GPC3." (PMID 40076777, 2025). "GPC3 is a cell-membrane-anchored HSPG proteoglycan for which the overexpression in HCC cancer cells correlates with a poor prognosis and that exerts its pro-tumoral function via the Wnt-signaling pathway." (PMID 38473265, 2024). "NK cells transduced with synNotch receptor targeting GPC3 antigen of cancer cells were able to secrete IL-12 into the tumor microenvironment directly, thus aiding CAR-T cells to infiltrate into cancer cells." (PMID 38726000, 2024). "Inhibition of Furin with CMK showed that GPC-3 cleavage is important for cancer cell survival as it generates the GPC-3C form observed in the sEVs of PHH." (PMID 37446098, 2023). "In cancer patients treated with the GPC3 peptide vaccine, serum levels of miR‐1228‐5p, miR‐193a‐5p and miR‐375‐3p were reported as predictive biomarkers of good response and improved overall survival." (PMID 37735815, 2023). "hGC33 scFv‐melittin MVs showed selectivity in inducing apoptosis between cancer cells and healthy cells; this was due to the specific binding between hGC33 scFv and GPC3." (PMID 38023709, 2023). "For instance, comparison between normal liver and kidney tissue and cancer involving these organs revealed high expression of GPC3 in liver hepatocellular carcinoma (LIHC) and low expression of GPC5 in kidney renal clear cell carcinoma (KIRC)." (PMID 36944188, 2023). "GPC3 has been evaluated as a cancer vaccine for some types of tumors, but little is known on the effects of GPC3 peptide‐based therapy on TYST." (PMID 37986544, 2023). "GPC3, one of the oncofetal transmembrane proteoglycans, has also been confirmed to be closely related to cancer cells’ growth, proliferation, invasion, and metastasis." (PMID 37366982, 2023). "Through the membrane-bound anti-GPC3 scFv, eFT-CNVs can efficiently bind to GPC3 overexpressing cancer cells followed by fusogen-mediated membrane fusion." (PMID 37291242, 2023). "In regard to cancer vaccines, by epigenetically activating the oncogene GPC-3 through PCAF recruitment, lncRNA-GPC3-AS1 was found to enhance HCC cell proliferation and migration." (PMID 35945536, 2022). "Glypicans are interesting cancer targets, and the latest developments in immunotherapy targeting GPC3 in cancer have shown great promise in clinical trials." (PMID 36676710, 2022). "GPC3 has exceptional cancer specificity and is currently being investigated as a global target for cancer-targeted therapies and immunotherapies." (PMID 35251989, 2022). "Glypican-3 (GPC3) is another vaccine that is assessed in phase 1 trial in patients with a history of HCV and HBV, which induces T-cell response against the glypican-3 on cancer cells." (PMID 36362398, 2022). "Detailed structural analysis and modulation of binding between uncoordinated-5 receptor D (Unc5D) and morphogen receptor glypican-3 (GPC3) reveal how finely balanced Unc5-GPC3 interactions regulate the migration of neuronal and cancer cells." (PMID 36240740, 2022). "On the basis of these points, this study revealed the utility of exosomes as siRNA carriers and the usefulness of anti-cancer treatments that involve knocking down GPC3 in vivo." (PMID 35456649, 2022). "GPC3 expression seems to be enhanced in cancers arising from tissues in which GPC3 expression is normally silenced, while its expression is inhibited in cancers derived from normal tissues that typically express GPC3." (PMID 36676710, 2022). "Recently, aberrant glypican-3 (GPC3) expression in cancers has gained considerable interest in cancer research." (PMID 36676710, 2022).
cancer (continued). "Heretofore, GPC3 and GPC1, which show excellent diagnostic effects in specific cancer types, respectively, have monopolized most studies of glypicans." (PMID 35345673, 2022). "The first GPC3-targeting ADCs, hYP7-PC and hYP7-DC, were developed with potency at picomolar concentrations against a panel of GPC3 positive cancer cells." (PMID 35281879, 2022). "Next, to validate the library performance, we conducted VHH screenings against liver cancer antigen glypican-3 (GPC3) and breast cancer antigen HER2 using cDNA display technology." (PMID 35225868, 2022). "Recently, chimeric antigen receptor T-cell therapy targeting a cancer stem cell marker Glypican 3 was tested for evaluating the safety profile in advanced HCC." (PMID 35955438, 2022). "Surprisingly, GPC3 has primarily been explored in relation to cancer biology and human malignancies." (PMID 36676710, 2022). "Pathways such as Wnt, Hedgehog, and YAP are often dysregulated in several types of cancer, and GPC3 has been shown to play a key role in the coordination of these pathways, even if it is not still well defined in several cases." (PMID 36142190, 2022). "Another study suggests that GPC3-possitive HCCs possess more metastatic potential since GPC3 expression promotes cancer cell proliferation and epithelial-mesenchymal transition (EMT)." (PMID 36518314, 2022). "GPC3 has two important properties that make it an optimal target for drug delivery: it is specific to HCC cancer cells, and it is bound to the cell membrane and protrudes from the cellular compartment." (PMID 36077433, 2022). "Glypican-3 (GPC3) is a hallmark of HCC, with the positive expression on 75% of HCC cells, and CD133 is a kind of cancer stem cell (CSC) maker that is also specifically expressed on HCC cells." (PMID 35879685, 2022). "Proteoglycan 4 was reported to inhibit carcinoma neovascularization, while glypican-3 and agrin increase the proliferation and angiogenesis of HCC cells." (PMID 36555545, 2022). "Glypican 3 (GPC3) is a heparan sulfate glycoprotein on the surface of cell membranes and is a specific antigen associated with cancer." (PMID 34552961, 2021). "While FAT1 is still a new candidate in cancer research, GPC3 has been investigated extensively as prognostic biomarker and therapeutic target." (PMID 33878524, 2021). "The revelation of GPC3 as a potential binding partner of FAT1 extracellular domain unfolds an opportunity to study potential triggers of FAT1 signaling in cancers." (PMID 33878524, 2021). "LATS2, MCC, DCC, RHOB, TRIM13, LIMD1, and GPC3 also strongly and positively regulated gene down-expression in cancer." (PMID 33580150, 2021). "GPC3-S-Fab, is an antibody Fab fragment based BiAb, and recruits NK cells to eliminate GPC3 positive cancer cells by linking the Fab of anti-GPC3 antibody to anti-CD16 single domain antibody." (PMID 34306031, 2021). "GPC3 is a specific target for cancer therapy; it has a high detection rate in the early stage of HCC, and with the development of HCC, its detection rate also increases." (PMID 34261411, 2021). "The expression patterns of GPC3 in different cancer types have been reported to be different, and its role is controversial." (PMID 34112123, 2021). "A bispecific antibody (GPC3-S-Fabs) was reported to recruit NK cells to target GPC3 positive cancer cells." (PMID 34306031, 2021). "Down-regulation of GPC3 with the use of specific siRNAs, miRNAs, or anti-GPC3 antibodies results in a decrease in cancer cell migration, metastasis, and invasion." (PMID 33562077, 2021). "Nonetheless, the binding affinity was excellent for GPC3-positive cancer cells, and further use of the antibodies for constructing ADCs was investigated." (PMID 32575828, 2020). "As for the intersection of the key gene set and key target genes, it is noteworthy that although GPC3 had not been used as the final independent prognostic indicator, it also confirmed the GPC3 over-expression in a variety of cancers." (PMID 32196072, 2020).
cancer (continued). "Specifically, MSLN promotes cancer proliferation and apoptosis resistance through NF-kB activation, while GPC-3 promotes cancer proliferation through sulfatase/Wnt- signaling pathway." (PMID 33344222, 2020). "Anchoring HN3 to the membrane of the exosomes using LAMP2, made HN3LC9-293exo to specifically enter the GPC3+ HuH-7 cancer cells than the GPC3− LO2 cells in a co-culture model." (PMID 33062407, 2020). "The major mechanism of anti-GPC3 antibody (GPC3Ab) against cancer cells is antibody-dependent cellular cytotoxicity and/or complement-dependent cytotoxicity." (PMID 31510063, 2019). "We identified GPC3 as a promising target for cancer immunotherapy and have been working on the development of cancer immunotherapeutic agents targeting it through clinical trials." (PMID 31024850, 2019). "Adoptive immunotherapy with TCR-transduced T cells is generally considered as having superior antitumor effects to peptide vaccine therapy, and their application to advanced cancers presenting GPC3 peptide is highly anticipated." (PMID 31024850, 2019). "Our study shows that GPC3 is significantly decreased on serum-derived exosomes from GEA patients in comparison to healthy donors or patients with a non-malignant disease, when we analyzed the occurrence of GPC3 on circulating extracellular vesicles." (PMID 31100935, 2019). "To further improve the clinical efficacy of cancer immunotherapy targeting GPC3, we are also developing next-generation therapeutic strategies using T cells engineered to express antigen-specific T-cell receptor or chimeric antigen receptor." (PMID 31024850, 2019). "While the role of GPC3 as a cancer marker and during liver proliferation, regeneration, and repair has been described, GPC3 is not canonically thought to be expressed in adult hepatocytes at homeostasis." (PMID 30891005, 2019). "In this review, we summarize the results of cancer immunotherapy targeting GPC3 based on our experience and outline the future prospects." (PMID 31024850, 2019). "The combination of an anti-GPC3 antibody and an immune checkpoint targeting antibody is also an attractive protocol for the treatment of GPC3-expressing cancers." (PMID 31510063, 2019). "It is presumed that GPC3 is cleaved between Arg358 and Ser359, which releases the N-terminal region as a soluble protein from cancer cells into the circulation." (PMID 31024850, 2019). "Herein, we summarize current insights into the role of GPC3 in regulating cancer development through Wnt and other signaling pathways, including YAP and hedgehog cascades." (PMID 31428581, 2019). "We identified GPC3 in a cDNA microarray screen of several tens of thousands of genes for novel cancer antigens." (PMID 31024850, 2019). "In the future, we envision an array of GPC3-based strategies, not only as cancer vaccines, but also in antibody therapy, adoptive immunotherapy with TCR- or CAR-transduced T cells, and others." (PMID 31024850, 2019). "In this review article, we summarize the results of clinical trials carried out by our team and describe the novel agent targeting the cancer-specific shared antigen, GPC3." (PMID 31024850, 2019). "As a representative molecule specifically expressed by cancer cells, glypican-3 (GPC3) in HCC has attracted attention." (PMID 31510063, 2019). "We also anticipate that plasma GPC3 will be validated as a biomarker for HCC or for evaluating the efficacy of cancer immunotherapy against GPC3." (PMID 31024850, 2019). "The levels of GPC-3 expression in the cancerous tissues were associated with poor ~ moderate differentiated grade (P < 0.001), HBV infection (P = 0.004), and periportal cancer embolus (P = 0.043)." (PMID 27286460, 2016). "Together, these findings suggest that loss of GPC3 activates the Erk1/2-FoxM1-MMP9 signaling axis, thereby promoting cancer cell dissemination." (PMID 27259271, 2016). "Glypican-3 (GPC3), a proteoglycan involved in the regulation of proliferation and survival, has been associated with cancer." (PMID 27507057, 2016).
cancer (continued). "The clinicopathologic features of GPC-3 expression in HCC patients were associated with poor ~ moderate differentiated grade, HBV infection, and periportal cancer embolus." (PMID 27286460, 2016). "We also showed that two humanized anti-GPC3 antibodies (hYP7 and hYP9.1b) in the IgG format induced antibody-dependent cell-mediated cytotoxicity and complement-dependent-cytotoxicity in GPC3-positive cancer cells." (PMID 27667400, 2016). "The induction of a specific GPC3 immune response is a crucial factor for the design of immunotherapeutic strategies against cancer." (PMID 25625609, 2015). "A vaccine that induces cytotoxic T lymphocytes (CTLs) is an ideal strategy for cancer, and glypican-3 (GPC3) is a potential option for HCC." (PMID 25354479, 2015). "GPC3 is downregulated in several cancers, which can result in uncontrolled cell growth and can also contribute to the malignant phenotype of some tumors." (PMID 25168166, 2014). "According to our results, M1 macrophages in GPC3 expressing cancer ascitic fluids increase on day 3 after inoculation with cancer cells." (PMID 24992906, 2014). "The percentage of CD206+/F4/80+ cells was 5.05% in the GPC3-expressing group and 14.7% in the control group on day 3 after inoculation with cancer cells." (PMID 24992906, 2014). "One previous study demonstrated that inhibiting GPC3 expression released hepatocyte carcinoma cells from G1 arrest and thus modulated cell cycle progression in this type of cancer." (PMID 25168166, 2014). "We also determined that the secretion levels of TNF-α and IL-12 were significantly higher in the ascitic fluids of the GPC3-expressing HM-1 cell-infected mice than in the control HM-1 cell-injected mice on day 7 after inoculation with cancer cells." (PMID 24992906, 2014). "We found the two cytokines were higher in ascitic fluids of GPC3 expression cancer than the control especially at an early time; it was similar to M1 macrophages in ascitic fluids." (PMID 24992906, 2014). "Next, we tested the reactivities of these CTL clones against cancer cell lines that expressed GPC3 and HLA-A*02:07." (PMID 23903757, 2013). "One CTL clone showed cytotoxicity against cancer cell lines that expressed endogenously the GPC3 peptide." (PMID 23903757, 2013). "The mechanisms regulating the transcription of GPC3 are of particular interest to understand the altered expression of GPC3 in cancer cells." (PMID 15083193, 2004). "Like GPC5, GPC3 regulates many cancer-progressive cascades, including Wnt, hedgehog, and FGF." (PMID 40688491, 2025). "We then conducted clinical trials of GPC3 peptide vaccines for hepatocellular carcinoma, ovarian clear cell carcinoma, and pediatric cancer, where we demonstrated multiple cases of partial response in advanced cancer and recurrence prevention." (PMID 40806530, 2025). "Therefore, in this study, we challenged ourselves to collect some common cancer membrane protein antigens, including GPC3, expressed in a wide range of solid cancers but only in limited amounts in normal tissues." (PMID 40076777, 2025). "GPC3 is currently considered the most promising cancer antigen in the GPC family." (PMID 40688491, 2025). "Mahati and colleagues recently demonstrated that anti-Glypican 3 (GPC3) single-stranded variable fragment (scFv)-modified MSC-Exos could be used for the delivery of anti-cancer agents in GPC3-expressing tumors, like GPC3-expressing HCC." (PMID 39936993, 2025). "However, the antibodies' high binding affinity for GPC3-positive cancer cells led to further research into using them to create ADCs." (PMID 40416124, 2025). "Recent studies suggest that the dual roles of GPC3 in cancer may be attributed to its structural features." (PMID 40422229, 2025). "Notably, seven children (male: three; female: four) with pediatric cancer who received the GPC3 vaccine have remained disease-free for approximately 10 years." (PMID 40806530, 2025).
cancer (continued). "In addition to the sparse research on the physiological functions of GPC3 the vast majority of scholarly attention has been directed towards its pathological implications in cancer." (PMID 40422229, 2025). "A chimeric antigen receptor-T (CAR-T) targeting GPC3 has also been developed for cancer treatment." (PMID 40688491, 2025). "The expression and roles of GPC3 in cancer are notably tissue-dependent." (PMID 40422229, 2025). "Clinically, GPC3 has been successfully employed as a serological biomarker for cancer detection." (PMID 40278256, 2025). "Thus, we identified 10 highly immunogenic cancer-specific antigens, including GPC3 and HSP105α, which are widely expressed in solid tumors." (PMID 40806530, 2025). "Furthermore, coupling human monoclonal antibody GC33 (ligand of GPC3) onto Macropa (named 225Ac-Macropa-GC33) can achieve targeted radiotherapy of GPC3-overexpressing HepG2 cancer cells." (PMID 39202907, 2024). "Studies have used GPC3+/CD3+ MSCS to induce CD3+ specific T cells to recognize GPC3+ cancer cells." (PMID 38005963, 2023). "GPC3 is a cancer-specific cell membrane protein and a promising target for cancer immunotherapy." (PMID 36509913, 2023). "Together with Afp and Igf2, the expression of stem cell markers Dlk1, Gpc3 and Epcam appeared to be higher in clusters 7 and 16, which may represent the bona fide cancer cells." (PMID 37414763, 2023). "We selected an antibody targeting the Wnt-binding site of GPC3 to construct a novel anti-GPC3 immunotoxin, which exhibited effective antitumor activity via PE toxin-mediated cytotoxicity and antibody fragment-mediated blocking of cancer signaling." (PMID 37626430, 2023). "A novel multi-functional nanostructure, galactose (GAL)- golden nanorods (GNR)-siRNA of GPC3(siGPC3) was found to produce both silencing of the GPC3 gene and photothermal action, and may be useful as a synergistic treatment for cancer." (PMID 35251989, 2022). "Upregulated genes in mEPCs, including IGF2, GPC3, S100A4, STMN1, and MDK, were semi-automatically assigned to the traditional cancer hallmark framework 15, including proliferative signaling, invasion/metastasis, genomic instability, immune response, and stem cell-like program." (PMID 36198671, 2022). "One member of the glypican family that has attracted the interest of cancer researchers is GPC3." (PMID 36676710, 2022). "Several studies have investigated the expression of GPC3 in many cancers." (PMID 36676710, 2022). "Mutations in GPC3 cause Simpson-Golabi-Behmel overgrowth syndrome (SGBS), a genetic disorder that presents with visceral and skeletal abnormalities and an increased risk of cancer." (PMID 36240740, 2022). "In conclusion, the F3 peptide could bind to GPC-3 in human cancer tissues specifically and showed great potential for further translational research." (PMID 34150644, 2021). "Ongoing clinical trials include the use of GC33 (codrituzumab), an anti-GPC3 antibody which has been found to debilitate cancer cells via antibody-dependent cellular cytotoxicity and/or complement-dependent cytotoxicity and has shown prognostic merit for HCC patients in phase II trials." (PMID 33878524, 2021). "ONCOMINE database was used to perform pan-cancer analysis on GPC3, GPX3 and PRICKLE1 expression." (PMID 34926458, 2021). "The IL-12- inducible GPC3-CAR-T cells could broaden the application of CAR-T-based immunotherapy to patients intolerant of cytoreductive chemotherapy and might provide an alternative therapeutic strategy for patients with GPC3+cancers." (PMID 34071188, 2021). "Moreover, immunohistochemical examination revealed that > 80% of the cancers tested expressed either HSP70 or GPC3." (PMID 32219501, 2020). "Furthermore, GC33 and YP7 are being developed for anti-GPC3 cancer therapies including CAR-T cells, bispecific T-cell engagers and ADCs." (PMID 32746924, 2020).